REN (renin)
Diseases named in the same sentence as REN in open-access papers (continued):
Sharing a sentence is not in itself a finding about the gene and the disease.
atrial fibrillation (continued). "It has also been reported that vitamin D is a negative modulator of the renin–angiotensin–aldosterone system, oxidative stress, and inflammation, resulting in myocardial remodeling and an increased risk for the development of atrial fibrillation." (PMID 40431432, 2025). "In patients with atrial fibrillation (AF), for instance, UA levels were associated with RAAS activation, indicating that renin activity and plasma aldosterone concentration (PAC) levels are positively correlated with UA levels." (PMID 39140032, 2024). "Additionally, the acute onset of atrial fibrillation may lead to the activation of neurohormones, the activation of the renal renin-angiotensin system, and result in disorders in water and sodium metabolism." (PMID 36899056, 2023). "Therefore, genetic variation in the RAS system may influence effect of renin-angiotensin system blockers on atrial fibrillation." (PMID 25723521, 2015). "Vitamin D, an antioxidant agent, plays an important role in the renin-angiotensin-aldosterone system (RAAS), helping to maintain blood pressure in a range that can decrease atrial remodeling happening in atrial fibrillation." (PMID 34326963, 2021). "Studies have indicated that the renin-angiotensin-aldosterone system (RAAS) has been shown to an important hormonal system in the initiation and pathogenesis of atrial fibrillation (AF)." (PMID 23724069, 2013). "Renin–angiotensin–aldosterone-system inhibitors markedly play an active role in the primary prevention of atrial fibrillation (AF), but the impact of angiotensin-converting enzyme inhibitors (ACEIs) or angiotensin receptor blockers (ARBs) on the mortality of patients with AF remains unclear." (PMID 35365067, 2022). "The main explanation might be that the combination medication with renin–angiotensin–aldosterone system (RAAS) inhibitors and beta-blockers appeared to prevent the new-onset atrial fibrillation in patients with left ventricular dysfunction." (PMID 34220493, 2021). "The results provide no support for the routine use of renin-angiotensin system inhibitors for the possible prevention of postoperative atrial fibrillation and adverse events in patients undergoing cardiac surgery." (PMID 31150082, 2019).
hyperaldosteronism (54 papers, 2005 to 2026). Overproduction of aldosterone by the adrenal glands, which may lead to hypokalemia and/or hypernatremia. "Both appeared to have episodic hyperaldosteronism, detected by serial aldosterone (Aldo) and renin measurements that identified variable diagnostic aldosterone-renin ratios (ARR)." (PMID 37291193, 2023). "In terms of the renin-aldosterone system, the majority of GS cases exhibit both hyperrenin activity and hyperaldosteronism, although one rare case report describes GS associated with elevated plasma renin activity and normoaldosteronism." (PMID 25140267, 2014). "The mechanism of hyperaldosteronism in the Pomc−/– model is probably secondary to the hypotensive effect of glucocorticoid deficiency which leads to activation of the renin–angiotensin system." (PMID 19170705, 2009). "Hair ALDO, with the inclusion of its precursors, may be a better diagnostic marker for hyperaldosteronism with utility in the interpretation of the aldosterone–renin ratio." (PMID 39610840, 2024). "While FMD-related RAS can lead to secondary hyperaldosteronism, this typically occurs with elevated renin." (PMID 41356982, 2025). "While spironolactone can help control blood pressure in both hyperaldosteronism and other forms of resistant hypertension, it can confound aldosterone and renin measurements." (PMID 41356982, 2025). "By contrast, secondary hyperaldosteronism arises when activation of the renin‐angiotensin system results in high renin activity; this stimulates aldosterone secretion." (PMID 40813337, 2025). "This excess mineralocorticoid receptor activation then leads to pseudohyperaldosteronism, which clinically mimics hyperaldosteronism but with suppression of both aldosterone and renin levels." (PMID 39807221, 2025). "Our understanding of hyperaldosteronism has been significantly improved with technological advancements that go beyond the scope of assessing renin and aldosterone levels." (PMID 40951055, 2025). "Volume depletion triggers the renin-angiotensin-aldosterone system, leading to secondary hyperaldosteronism." (PMID 39268309, 2024). "When screening for hyperaldosteronism, it is recommended to perform plasma aldosterone and renin sampling and aldosterone/renin ratio." (PMID 37629095, 2023). "Hyperaldosteronism with elevated plasma aldosterone (109 ng/dl, reference 2–70 ng/dl) and low renin (0.10 ng/ml/h, reference 0.25–5.82 ng/ml/h) was also documented." (PMID 36208199, 2023). "Because of the unusual presentation for hyperaldosteronism, a comprehensive profile of renin-angiotensin-aldosterone system (RAAS) peptides was performed." (PMID 34859924, 2021). "The hyperaldosteronism can be explained by increased renin secretion secondary to the mass effect of the tumor compressing the renal artery." (PMID 31500669, 2019). "When plasma aldosterone and renin were examined, the tests revealed hyporeninemic hyperaldosteronism, by contrast, patients with GS usually present with high levels of plasma renin." (PMID 31498018, 2019). "The condition was first described by J Conn, who further distinguished primary and secondary hyperaldosteronism on the basis of plasma renin levels, PA being characterized by renin suppression." (PMID 20482833, 2010). "Using the aldosterone: renin ratio to find possible cases, Gordon and colleagues reported that hyperaldosteronism was more common than suspected, with 8% of cases referred to his clinic having this condition." (PMID 17490489, 2007). "The clinical recovery timeframe of licorice‐induced hyperaldosteronism varies and may take up to 6 months for the renin–angiotensin–aldosterone axis to normalize, owing to the long half‐life of glycyrrhetic acid." (PMID 39807221, 2025). "Furthermore, as OHSS represents a hypovolemic state, secondary hyperaldosteronism ensues with subsequent activation of the renin-angiotensin-aldosterone system." (PMID 34431837, 2021).
hyperaldosteronism (continued). "This suggests that adrenal GRK2 may be a molecular link connecting the sympathetic nervous and renin-angiotensin systems at the level of the adrenal cortex and that its inhibition might be therapeutically advantageous in hyperaldosteronism-related conditions." (PMID 31963151, 2020). "Kcnk3 (TASK-1) knockout mice show the expression of Cyp11b2 in the reticulo-fasciculata zone instead of in the ZG and develop severe hyperaldosteronism (including hypokalemia and low renin levels) remediable by glucocorticoids, representing clinical features of FH-I90." (PMID 31695023, 2019). "Hypernatremia diagnostic work-up, combined with low potassium levels, normal renin activity value, and mild metabolic alkalosis, was compatible with hyperaldosteronism (aldosterone 392 ng/dL (reference values: 19–141) and renin 4920 ng/dL/hr (reference values: 1100–16700))." (PMID 26229701, 2015). "The failure of saline infusion to suppress renin secretion after cessation of gastrointestinal fluid losses and at appropriate blood pressure for her age and state of pregnancy pointed to the need to identify a separate basis for renin-stimulated hyperaldosteronism." (PMID 27579038, 2016). "The ensuing salt-wasting and volume depletion activate the renin-angiotensin-aldosterone system (RAAS), leading to hyperaldosteronism." (PMID 41393191, 2025). "This cohort did not have data serum aldosterone level and plasma renin activity in evaluating the state of hyperaldosteronism." (PMID 37568223, 2023). "However, the Plasma Renin Activity (PRA) test, which is the indicator of hyperaldosteronism, was carried out." (PMID 15811183, 2005). "Recent evidence shows that hyperaldosteronism is not simply a consequence of having an elevated aldosterone–renin ratio, but rather is characterized by a spectrum of increased aldosterone production independent of renin [20•]." (PMID 35384577, 2022). "PA is characterized by hyperaldosteronism that is independent of renin and angiotensin II (thus renin-independent aldosteronism) that results in excessive MR activation, increases intra-vascular volume and blood pressure, and results in renal, vascular, and cardiac disease, and higher mortality." (PMID 29439489, 2018). "Moreover, primary sodium retention would be expected to result in suppressed plasma renin activity yet this was actually slightly elevated in the 4 patients with these data available, albeit without concomitant hyperaldosteronism." (PMID 25358339, 2014). "Furthermore, the reduction in renin and the absence of an increase in adrenocorticotropic hormone observed in the present proteomic analysis are also consistent with a direct action of torcetrapib leading to hyperaldosteronism." (PMID 28974520, 2018).
Sepsis (54 papers, 2010 to 2026). Sepsis is defined as life-threatening organ dysfunction caused by a dysregulated host response to infection. "Direct renin levels of 64 samples were assayed from 32 sepsis-associated ARDS patients (50% male; mean ± SD, 55 ± 13.8 years old)." (PMID 38509149, 2024). "In contrast, our study had 32 sepsis-associated ARDS patients with 2 measurements of renin levels per patient." (PMID 38509149, 2024). "We sought to determine if elevated plasma renin levels signaled worse outcomes in the sepsis-associated ARDS patients treated at our institution." (PMID 38509149, 2024). "We investigated renin as a biomarker for sepsis-associated ARDS instead of ACE because renin is upstream to both ACE and ACE216." (PMID 38509149, 2024). "Future studies evaluating renin levels in patients with sepsis-associated ARDS are needed to validate these findings." (PMID 38509149, 2024). "The present study seeks to link plasma renin levels and 30-day mortality in sepsis-associated ARDS patients treated at our institution." (PMID 38509149, 2024). "The sepsis-associated deregulation of RAAS frequently manifests as increased activity of plasma renin and increased concentrations of angiotensin I (ANG I) and ANG II, but with concurrent low aldosterone." (PMID 36012398, 2022). "In six observational studies that examined the risk of AKI development in sepsis, pre-existing renal dysfunction, aging, and the use of renin-angiotensin-aldosterone system inhibitors were found to be associated with AKI development in sepsis." (PMID 30123509, 2018). "In 6 observational studies that examined the risk of AKI development in sepsis, pre-existing renal dysfunction, aging, and the use of renin–angiotensin–aldosterone system inhibitors were found to be associated with AKI development in sepsis." (PMID 30039479, 2018). "Despite these limitations, renin emerges as a promising biomarker for sepsis-associated ARDS." (PMID 38509149, 2024). "Our study provides novel evidence that renin may be a new biomarker to prognosticate sepsis-associated ARDS mortality." (PMID 38509149, 2024). "However, both AT1 and AT2 pathways are known to involve renin, making renin a promising target for further investigation as a potential biomarker for sepsis-associated ARDS." (PMID 38509149, 2024). "In this study, we found that renin may be a novel biomarker that has prognostic value for patients with sepsis-associated ARDS." (PMID 38509149, 2024). "In two observational studies that examined whether the use of renin–angiotensin–aldosterone system inhibitors was a risk factor for AKI development in sepsis, the risk was found to be approximately twice as high when using these drugs than when not using them." (PMID 30039479, 2018). "Thus, the dysregulation of the renin-angiotensin-aldosterone system and the dysregulation of the monocyte/macrophage activation or the T-cell activation may be involved in sepsis-induced associated organ failure." (PMID 34072601, 2021). "In this study, the authors divided the cohort into a normal renin sepsis group and a high renin sepsis group, comparing both to a control group of healthy subjects." (PMID 40126750, 2025). "Instead, increased ACE2 and DPP3 expression were observed, with serum DPP3 higher in both normal- and high-renin sepsis groups compared to controls." (PMID 41226854, 2025). "Sepsis 110 (66.67%), volume depletion 69 (41.82%), and use of the renin-angiotensin-aldosterone system (RAAS) blockers 45 (27.77%) age >65 42 (25.45%) were the most common AKI risk factors." (PMID 40322332, 2025). "Previous studies have shown that Ang II and renin levels in sepsis correlate significantly with disease severity and mortality." (PMID 40880342, 2025). "Sepsis can activate the renin–angiotensin–aldosterone system (RAAS), promoting increased production of angiotensin II (Ang-II), exacerbating vasoconstriction and renal hypoperfusion, and ultimately leading to renal ischemic injury." (PMID 41041277, 2025).
Sepsis (continued). "In a cohort of sepsis-associated ARDS patients, Renin was found to be a novel biomarker with the potential to prognosticate hospital mortality." (PMID 38509149, 2024). "Animal studies, for example, have shown that blockade of the brain renin–angiotensin–aldosterone system appears to prevent sympathetic hyperactivity and markedly attenuates LV dysfunction during sepsis." (PMID 38811967, 2024). "The detection of such a signal in DARK-Sepsis would justify the use of renin or DPP3 as biomarkers to enrich the study population of a large clinical efficacy trial of AT2 in septic shock." (PMID 38475822, 2024). "Dysregulation of the renin–angiotensin–aldosterone-system (RAAS) in sepsis is a complex and early phenomenon with a likely significant contribution to organ failure and patient outcomes." (PMID 39593182, 2024). "Renin has been identified as a biomarker in several different patient populations including sepsis, cardiovascular disease, and cardiac surgery, where renin was strongly associated with in-hospital mortality." (PMID 37842390, 2023). "The plausible explanation is that sepsis results in renin-angiotensin-aldosterone system activation, angiotensin II production which is an inflammatory agent and is associated with organ failure and mortality." (PMID 36890975, 2023). "This study aimed to assess the usefulness of renin as a marker of tissue hypoperfusion in patients with sepsis and septic shock." (PMID 36012398, 2022). "The levels of renin in patients with septic shock were significantly higher than those in patients with sepsis." (PMID 36012398, 2022). "Further, the level of renin in patients with septic shock was significantly higher than in patients with sepsis." (PMID 36012398, 2022). "There was a significant difference in renin concentration between sepsis and septic shock patients on the first (45.8 and 103.4 pg/mL, respectively) and third (24.7 and 102.1 pg/mL, respectively) days." (PMID 36012398, 2022). "In this study, we attempted to evaluate the usefulness of renin, besides lactate levels, as an additional biomarker of hypoperfusion in the course of sepsis and septic shock." (PMID 36012398, 2022). "Regarding sepsis clinical scores, renin concentration positively correlated solely with SOFA on the third and fifth study days." (PMID 36012398, 2022). "In a cohort study of 30 critically ill patients with severe sepsis compared to 10 healthy controls, plasma renin activity (PRA) and angiotensin II were higher at 8- and 24-h following the recognition of organ dysfunction." (PMID 34391450, 2021). "Current research has addressed the involvement of the renin–angiotensin–aldosterone system (RAAS) in sepsis and AKI." (PMID 32272738, 2020). "In recent years, the renin-angiotensin system (RAS) has received increasing attention in the field of sepsis, but the clinical research results on RAS are inconsistent." (PMID 24940436, 2014). "The renin-angiotensin system (RAS) is activated in sepsis, and recent studies implicate Ang II in the pathogenesis of acute lung injury in animal models." (PMID 20175923, 2010). "High renin levels could play an important role in immune system dysregulation in sepsis and septic shock." (PMID 40880376, 2025). "Our study aims to assess the prognostic value of plasma renin levels over two time points in a cohort of non-COVID sepsis-associated ARDS patients as a predictor of hospital mortality." (PMID 38509149, 2024). "In this cohort of sepsis-associated ARDS patients, Day 3 Renin was found to be a potential biomarker that could prognosticate hospital mortality." (PMID 38509149, 2024). "Renin was a strong predictor of mortality in patients with sepsis and septic shock." (PMID 36012398, 2022). "Renin is a strong predictor of mortality in patients with sepsis and septic shock." (PMID 36012398, 2022).